C19orf67 (chromosome 19 open reading frame 67)
Tractability: No criterion of Open Targets' tractability assessment is met for any kind of drug.
Gene: Protein-coding gene on chromosome 19 (14,081,624 to 14,085,875, reverse strand). Ensembl gene ENSG00000188032.
Subcellular location (Human Protein Atlas): Cytosol; Nucleoli; Nucleoplasm
Genetic constraint (gnomAD): Loss-of-function variants: 30 observed, 39.93 expected, observed/expected ratio (o/e) 0.75, 90% interval 0.56 to 1.02. The upper end of that interval is the gene's LOEUF score, 1.02, which puts it in group 4 of 6, group 1 being the genes least tolerant of losing a copy. Missense variants: 421 observed, 458.14 expected, observed/expected ratio (o/e) 0.92, 90% interval 0.85 to 1. Synonymous variants: 242 observed, 200.23 expected, observed/expected ratio (o/e) 1.21, 90% interval 1.09 to 1.34.
Homologues: Orthologues: chimpanzee C19H19orf67 (99% identical), macaque C19H19orf67 (96% identical), dog C19orf67 (85% identical), pig C19orf67 (84% identical), mouse 1700067K01Rik (80% identical), rabbit C19orf67 (80% identical), rat C19h19orf67 (78% identical), guinea pig C19orf67 (72% identical), zebrafish si:ch211-214c7.5 (33% identical).